TK1 (thymidine kinase 1)
Diseases named in the same sentence as TK1 in open-access papers (continued):
Sharing a sentence is not in itself a finding about the gene and the disease.
Pleural effusion (1 paper, 2019). The presence of an excessive amount of fluid in the pleural cavity. "The TK1 concentration in pleural effusion was significantly higher in MPE than BPE (P < 0.001), and patients with MPE could be distinguished by an optimal cutoff value of 3.10 pmol/L with a sensitivity of 0.894 and a specificity of 0.800." (PMID 30985967, 2019). "TK1 concentrations in pleural effusion were measured by chemiluminescence dot blot assays." (PMID 30985967, 2019).
Sepsis (1 paper, 2022). Sepsis is defined as life-threatening organ dysfunction caused by a dysregulated host response to infection. "This is also the first time that we reported the studies on RRM2, TK1, and TYMS in sepsis." (PMID 35082972, 2022).
thyroid nodule (1 paper, 2019). A small circumscribed mass in the THYROID GLAND that can be of neoplastic growth or non-neoplastic abnormality. "We first analyzed the serum TK1 protein levels from the subjects who underwent physical examination in our hospital and found that serum TK1 levels were significantly higher in the subjects with thyroid nodules compared to the normal subjects." (PMID 32064235, 2019). "In this study, it was found that serum TK1 levels were markedly increased in the patients with thyroid nodules." (PMID 32064235, 2019). "In this study, we found that serum TK1 levels were markedly increased in the patients with thyroid nodules." (PMID 32064235, 2019). "In this study, we identified the upregulation of TK1 in the serum of patients with thyroid nodules." (PMID 32064235, 2019).
uveal melanoma (1 paper, 2023). A melanoma derived from melanocytes of the uveal tract. "Here, we evaluated whether activity of TK1 in plasma could be used in uveal melanoma to monitor tumor responses." (PMID 37377898, 2023). "Therefore, in uveal melanoma, larger and additional studies, including multiple blood sampling, are needed to further evaluate TK1 as a potential biomarker." (PMID 37377898, 2023).
tumor (195 papers, 2007 to 2026). "TK1 activity is often elevated in proliferating cells and has been associated with tumor progression in various cancers." (PMID 40599331, 2025). "Elevated TK1 expression has been associated with poor prognosis, increased tumor burden, and higher metastatic potential." (PMID 40564887, 2025). "TK1 is vital in cellular proliferation and DNA repair and has been implicated in tumour development and progression." (PMID 40699738, 2025). "We further investigated the correlation between TK1 and immune cells and found that TK1 exhibited a close association with the increased tumor infiltration of antigen-presenting cells, including dendritic cells (P < 8.25e-06) and B cells (P < 4.16e-11)." (PMID 39403328, 2024). "Tumor-associated TK1 mRNA-responsive DNA nanospheres (DNA-NS) that encapsulate doxorubicin were purposed for tumor detection and chemotherapy." (PMID 38672671, 2024). "It has been found that TK1 expression is high in cancer patients and high serum TK1 levels are usually associated with cancer stage and increased tumor size." (PMID 36874006, 2023). "In TISIDB, the associations between 28 tumor-infiltrating lymphocytes and TK1 expression were investigated in detail." (PMID 36831773, 2023). "Using TIMER, we explored the associations between TK1 expression and six tumor-immune cell infiltration levels." (PMID 36831773, 2023). "To verify the role of TK1 as a key player in the risk score as well as a tumor promoter in TNBC, we performed several functional experiments to detect the migration, invasion, and proliferation abilities of the control and siRNA-mediated knockdown groups." (PMID 37767092, 2023). "Using the TISIDB database, we also investigated the association between 28 tumor-infiltrating lymphocytes and TK1 expression in detail." (PMID 36831773, 2023). "There is a high production of this enzyme in fast‐proliferating neoplastic cells, and increased serum activity is caused by the leakage of TK1 after their death; thus, the TK1 activity in serum correlates with the proliferative activity of the tumour." (PMID 36495211, 2023). "Trifluridine, the active component of FTD/TPI, is incorporated into tumour DNA, causing DNA damage after phosphorylation by the enzyme TK1." (PMID 36291880, 2022). "This study found that TK1 was overexpressed in PCa, and its contents were linked to tumor stage and prognosis." (PMID 36035114, 2022). "In PCa, the content of TK1 and its methylation status were linked to tumor-invading immune cells and immunomodulators." (PMID 36035114, 2022). "The expression of TK1 along with its methylation status was found to be linked to tumor-invading immune cells, as well as PCa immunomodulators." (PMID 36035114, 2022). "We found that TK1 was remarkably overexpressed in PCa and that TK1 content was linked to tumor prognosis in individuals with PCa." (PMID 36035114, 2022). "In an earlier study, we explored the possibility to use the concentration of TK1 in blood as a marker of tumor cell loss to predict early during chemotherapy pathological tumor response." (PMID 34771604, 2021). "In other words, whereas cell death in tumours is associated with a significant release of TK1, normal tissues must have functions preventing this release." (PMID 32423477, 2020). "To summarize, other tissue proliferation biomarkers such as Ki-67 have been shown to be inconsistent in certain cancer types, whereas TK1 being closely linked to cell growth stage more closely reflects tumor proliferation." (PMID 33292474, 2020). "Here, we evaluated the usefulness of a metric of cell loss, defined as the ratio between the concentration of TK1 in serum and tumor volume, for early prediction of the outcome of chemotherapy in patients with BC." (PMID 32423477, 2020). "The present study introduces a measure of cell loss, obtained by combining the serum level of TK1, released from disrupted tumour cells, with tumour volume." (PMID 32423477, 2020).
tumor (continued). "A cell-loss metric, based on serum levels of TK1, released from disrupted tumour cells, and tumour volume, reveal tumour response early during neoadjuvant treatment." (PMID 32423477, 2020). "CTCs count and ESR1/PIK3CA mutations in circulating tumor DNA were performed and correlated with TK1 activity." (PMID 29662653, 2018). "The significant correlation between TK1 LI and TK1 intensity shows that higher numbers of proliferating tumor cells are linked to an elevated synthesis rate of TK1." (PMID 23693054, 2013). "Serum thymidine kinase 1 (STK1) levels have been used for monitoring tumor therapy and for assessing the risk of recurrence and prognosis of survival in hematological malignancies as well as in solid tumors." (PMID 24649267, 2013). "Elevated TK1 levels with increasing Gleason scores suggested that TK1 may be responsive to cellular proliferation associated with more aggressive tumour pathology." (PMID 40830177, 2025). "Furthermore, elevated serum TK1 levels have been proposed as biomarkers for tumor burden, recurrence risk, and treatment resistance." (PMID 40564887, 2025). "In the blood, elevated TK1 levels are associated with tumor progression." (PMID 39006942, 2024). "Notably, TK1 was identified as a potential tumor-associated antigen in THCA through four gene sets, including over-expressed, DFS-related (disease free survival-related), mutational, and amplified genes." (PMID 39403328, 2024). "TK1 expression is also a prerequisite for the activation of certain thymidine analogues used in chemotherapy and as a diagnostic and prognostic biomarker for neoplastic disease." (PMID 34906077, 2021). "In contrast, serum TK1 has been utilized as a diagnostic in human oncology since the 1980s, and therefore this value has been well‐established throughout the course of disease, even preceding the diagnosis of neoplasia." (PMID 34359096, 2021). "The observation that TK1 overexpression in LUAD is predictive of tumor aggressiveness, as evidenced by its significant association with poor prognosis and LUAD recurrence, led us to ask whether TK1 is important for LUAD tumor growth and metastasis." (PMID 31589613, 2019). "Thus, our findings indicate that the loss of GDF15 expression and reduced RhoA activity resulting from loss of TK1 via shRNA silencing leads to reduced tumor and metastatic activity in LUAD cells." (PMID 31589613, 2019). "The frequencies of this fusion event decreased from the adjacent tissues (29.2%) to tumors the (16.7%), suggesting that a truncated thymidine Kinase1 (TK1) caused by the fusion event might be deleterious and be selected against during tumor progression." (PMID 28412734, 2017). "The frequencies of this fusion event decreased from the adjacent tissues (29.2%) to the tumors (16.7%), suggesting that a truncated thymidine Kinase1 (TK1) caused by the fusion event might be deleterious and be selected against during tumor progression." (PMID 28412734, 2017). "Attempts to define these presumed structural differences are ongoing and may lead to the development of an in vitro diagnostic test specific for serum TK1 in patients with different tumor diseases." (PMID 25881026, 2015). "More recently, it has been shown that TK1 is upregulated in different tumor types in response to DNA damage, and that the cellular response to genotoxins causes nuclear localization of TK1; an interesting finding given that the salvage enzyme has previously been regarded as solely cytoplasmic." (PMID 25152750, 2014). "In addition, another study found that TK1 expression levels were associated with tumour grade and Gleason score, suggesting that higher TK1 expression could be linked to more aggressive prostate cancers." (PMID 40830177, 2025).
tumor (continued). "Thus, increased blood concentrations of TK1 might reflect tumor cell loss, which is an important factor of tumor growth." (PMID 36982234, 2023). "Moreover, we also found that the functions of TK1 were strongly associated with related signaling pathways, including cell cycle, cell division, and mitotic cell cycle phase transition, thereby promoting tumor malignant behavior." (PMID 35559045, 2022). "Thus, the activity of TK1, significantly increased in haematopoietic tumours, may be interesting in terms of diagnostic performances mainly for these specific tumours." (PMID 35815441, 2022). "Furthermore, monoclonal antibodies could potentially be exploited to detect TK1 on tumor cells, and, therefore, determine tumor burden in cancer patients in a diagnostic approach." (PMID 35203388, 2022). "Reductions in TK-1, a marker of tumor proliferation, and LDH, associated with hypoxia and tumor burden, further indicate the potential of rcIL-15 to modulate the tumor microenvironment." (PMID 40520425, 2025). "When tumour cells proliferate, the normal cell cycle regulation is broken, and TK1 is released into the blood so that the TK1 can reflect the proliferation rate of tumour cells." (PMID 40837360, 2025). "Although TK1 is broadly upregulated across multiple tumor types, its oncogenic role appears to be context dependent and varies by cancer type." (PMID 40564887, 2025). "TK1 mRNA, a biomarker of tumor growth, initiates hybridization and results in fluorescence recovery, which built the foundation for identifying the expression level changes in living cells." (PMID 40942076, 2025). "In contrast, TK1 showed consistent and tumor-enriched expression across multiple cancer types and minimal expression in normal tissues—with the exception of KICH—supporting its relevance as a more cancer-selective biomarker." (PMID 40564887, 2025). "Immunohistochemical analysis confirmed increased nuclear expression of H3.2 (H3C14), decreased CNT3 levels and increased TK1 levels in H3C14‐overexpressing tumours." (PMID 41159684, 2025). "When the cCRP was applied to the entire cohort of tumor samples, the ROC curve analysis demonstrated a similar area under the curve (AUC) of 0.70 compared to the canine TK1 ELISA with a sensitivity of 50% at a specificity of 95%." (PMID 40351765, 2025). "In the present study, the serum tumor markers survivin, Ki-67, and TK1 as well as a calculated SLR were investigated in dogs with different ND." (PMID 40260215, 2025). "In pan-cancer analyses, TK1 has been shown to mediate cell proliferation and promote tumor progression." (PMID 40416783, 2025). "Remarkably, we have shown the capability of this nanoprobe in the discrimination of cells with different TK1 mRNA expressions and multiplexed detection of two other tumor-related mRNAs, allowing for accurate measurement in living cells." (PMID 40942076, 2025). "Outcome measures included tumor response rates, tumor biomarker levels (TK-1, LDH, β2-microglobulin), quality of life (QOL) assessments, and adverse event monitoring." (PMID 40520425, 2025). "Both the TK1-ELISA and cCRP levels were significantly higher in the tumor group compared to healthy controls (p < 0.0001)." (PMID 40351765, 2025). "This aligns with clinical observations from the TCGA and CPTAC datasets, where TK1 expression was positively correlated with lymph node involvement and advanced tumor stage." (PMID 40564887, 2025). "TK1 exhibits cell cycle-dependent activity in the cytoplasm, with high activity in rapidly dividing cells, including stem cells and tumor cells; however, it is ubiquitinated and degraded in slow-dividing cells or cells with less active DNA replication." (PMID 40571767, 2025). "TK1 is a special cytoplasmic kinase catalyses thymidine to 1-phosphothymidylate and is an essential precursor for DNA synthesis in tumour cells." (PMID 40837360, 2025).
tumor (continued). "For instance, thymidine kinase 1 (TK1), an enzyme involved in DNA synthesis, exhibits high activity in tumor cells, leading to increased incorporation of thymidine." (PMID 39922049, 2025). "Serum TK1 expression is increased in dogs with neoplastic diseases, especially those with lymphomas." (PMID 40260215, 2025). "FLT tumor uptake is thought to be correlated with thymidine kinase-1 (TK1) activity in the thymidine salvage pathway." (PMID 37856073, 2024). "TK1 positive cells mainly localize in tumor area, and Treg cell infiltration in TNBC tissues was associated with high expression of TK1." (PMID 39749323, 2024). "TK1 is usually elevated in cancer patients' serum, making the enzyme a valuable tumor proliferation biomarker that strongly correlates with cancer stage and metastatic capabilities." (PMID 39006942, 2024). "Human TK1 protein concentration and activity in serum are closely related to DNA synthesis, and assessment of tumor proliferation rate is recommended in clinical oncology." (PMID 38887267, 2024). "In UCEC, total promoter region methylation level of TK1 was quietly lower than normal tissue suggesting that TK1 was an active condition in tumor tissues." (PMID 38480789, 2024). "For the first time, serum thymidine kinase 1 protein (STK1p), a tumor cell proliferating biomarker, was combined with ultrasound parameters to construct a novel nomogram model for the clinical prevention of CLNM in PTC pre-surgery." (PMID 38887267, 2024). "In highly proliferating cells, such as tumor cells, the TK1 enzyme activity is elevated, and its activity is considered an essential cellular proliferation tumor biomarker." (PMID 39006942, 2024). "Thymidine kinase (TK1), another important kinase in pyrimidine salvage, is also highly expressed in tumor cells and regarded as an important tumor marker." (PMID 36994237, 2023). "Results of the spatial transcriptome analysis reveals that TK1-positive expressed cells primarily localize in the tumor cells." (PMID 37767092, 2023). "Specifically, 20 out of the 39 cancer types tested showed significant TK1 elevation in tumor tissue when compared to adjacent healthy tissue." (PMID 38033034, 2023). "A noninvasive serological tumour proliferation rate detection of TK1 activity assay was considered in the clinical setting in the 1980s, and then, the isotope serum TK1 activity (STK1a) assay was improved to nonisotope technology." (PMID 36969497, 2023). "Normal patient samples showed a higher level of methylation in the TK1 promoter when compared to primary BRCA tumor samples (p = 1.11 x 10−16)." (PMID 38033034, 2023). "To confirm the TK1 protein expression, we assessed the expression of TK1 in normal cells and tumor cell lines." (PMID 36831773, 2023). "Serum TK1 is a biomarker that reflects accelerated cell proliferation and cell lysis both in normal and tumor cells." (PMID 37808109, 2023). "TK1 is a reliable tumour proliferation and prognostic biomarker that can be used for all types of tumours." (PMID 36969497, 2023). "Plasma TK1 has previously been shown to be a prognostic marker for survival as it is a reflection of the tumour burden and was similarly demonstrated in our study independently of its effect on 18F-FLT uptake." (PMID 37509378, 2023). "In this study, we analyzed TK1 expression with infiltration levels of six tumor-immune cells by using the TIMER database." (PMID 36831773, 2023). "This leads to the release of TK1 protein into the blood stream originating from disrupted tumor cells." (PMID 37808109, 2023). "Serum thymidine kinase 1 protein (STK1p) concentration has been used successfully as a reliable proliferating serum biomarker in early tumour discovery and clinical settings." (PMID 36969497, 2023). "We then developed a nomogram to predict 1-year, 3-year, and 5-year OS by using eight prognostic factors: age, tumor type, WHO tumor grade, IDH mutation status, 1p19q codeletion status, chemotherapy, radiotherapy, and TK1 expression." (PMID 36831773, 2023).